B3GNT9 (UDP-GlcNAc:betaGal beta-1,3-N-acetylglucosaminyltransferase 9)
Synonyms: MGC4655
Tractability: Antibody: UniProt predicts a signal peptide or a membrane-spanning region.
Gene: Protein-coding gene on chromosome 16 (67,148,104 to 67,151,260, reverse strand). Ensembl gene ENSG00000237172.
Subcellular location: Golgi apparatus membrane
Subcellular location (Human Protein Atlas): Golgi apparatus; Nucleoli fibrillar center
Pathways (Reactome):
Metabolism of proteins: O-linked glycosylation of mucins
Gene Ontology:
Molecular function: UDP-glycosyltransferase activity; hexosyltransferase activity
Biological process: poly-N-acetyllactosamine biosynthetic process; carbohydrate derivative metabolic process; glycoprotein biosynthetic process
Cellular component: Golgi membrane; membrane
Genetic constraint (gnomAD): Loss-of-function variants: 3 observed, 1.71 expected, observed/expected ratio (o/e) 1.75, 90% interval 0.61 to 1.94. That is too few expected variants to judge how well the gene tolerates losing a copy. Missense variants: 669 observed, 500.33 expected, observed/expected ratio (o/e) 1.34, 90% interval 1.25 to 1.42. Synonymous variants: 359 observed, 236.1 expected, observed/expected ratio (o/e) 1.52, 90% interval 1.39 to 1.66.
Homologues: Orthologues: chimpanzee B3GNT9 (99% identical), macaque B3GNT9 (97% identical), dog B3GNT9 (88% identical), pig B3GNT9 (88% identical), guinea pig B3GNT9 (87% identical), rat B3gnt9 (84% identical), mouse B3gnt9 (83% identical), tropical clawed frog b3gnt9 (50% identical), zebrafish b3gnt9 (47% identical), Drosophila melanogaster brn (23% identical), Caenorhabditis elegans bre-5 (21% identical), Caenorhabditis elegans F21C10.3 (9% identical), and 1 more. Paralogues in human: B3GNT7 (40% identical), B3GNT4 (37% identical), B3GNT6 (36% identical), B3GNT2 (35% identical), B3GNT3 (34% identical), B3GNT8 (29% identical), B3GNT5 (24% identical), B3GALT4 (23% identical), B3GALT2 (22% identical), B3GALNT1 (22% identical), B3GALT5 (21% identical), B3GALT6 (21% identical), and 3 more.
Diseases named in the same sentence as B3GNT9 in open-access papers:
B3GNT9 is named in the same sentence as 16 diseases in open-access papers, as found by Europe PMC text mining. Sharing a sentence is not in itself a finding about the gene and the disease. The quoted sentences say what the papers report.
glioblastoma (1 paper, 2023). The most malignant astrocytic tumor (WHO grade IV). "We investigated whether the expression of β3GNT9 was associated with immune infiltration in glioblastoma using the online database TIMER." (PMID 37771444, 2023). "Through qRT-PCR, we found the expression level of β3GNT9 was higher than that of normal astroglia in most cell lines of glioblastoma, which is in tune with the conclusion gleaned from relevant analysis using biological information technology." (PMID 37771444, 2023). "These suggested that β3GNT9 silencing inhibited the migration and invasion capacity of glioblastoma cells." (PMID 37771444, 2023). "Further exploration of the relationship between β3GNT9 and clinically relevant indicators of glioblastoma suggested that patients older than 65 years of age had higher β3GNT9 expression than patients of or under 65 years of age (P<0.05)." (PMID 37771444, 2023). "The findings indicate that increased β3GNT9 expression in glioblastoma can affect the immune microenvironment of glioblastoma and promote its migration and invasion." (PMID 37771444, 2023). "In conclusion, β3GNT9 demonstrates upregulated expression in glioblastoma, affecting the immune response of tumors and the immune microenvironment, especially macrophage and NK cells." (PMID 37771444, 2023). "As such, we propose that β3GNT9 can promote glioblastoma cell proliferation through affecting the metabolism of glioblastoma." (PMID 37771444, 2023). "Consistent with previous studies, the current study found β3GNT9 expression in glioblastoma is correlated negatively with tumor purity, but positively with macrophage enrichment." (PMID 37771444, 2023). "Overall, our study has proved for the first time that high levels of β3GNT9 expression are related to the poor prognosis of glioblastoma and can serve as an indicator of glioblastoma." (PMID 37771444, 2023). "We made the first analysis of the high β3GNT9 expression in glioblastoma patients’ tissues, and found that it is significantly and negatively correlated to the prognosis of patients with glioblastoma." (PMID 37771444, 2023). "β3GNT9 expression in glioblastoma group was significantly higher than that in normal brain tissue group (P<0.05)." (PMID 37771444, 2023). "The results showed that the expression of β3GNT9 in glioblastoma tissues was significantly higher than that in normal tissues (P<0.05)." (PMID 37771444, 2023). "Radiotherapy is a protective prognostic indicator for glioblastoma (P<0.05), whereas high expression of β3GNT9 is an independent prognostic indicator for glioblastoma." (PMID 37771444, 2023). "Through the cell scratch invasion assays, this study also made the first attempt to find that the silencing of β3GNT9 constrained the migration and invasion of glioblastoma." (PMID 37771444, 2023). "High levels of β3GNT9 promote the migration and invasion of glioblastoma, which in turn leads to poor patient prognosis." (PMID 37771444, 2023). "While we have gained preliminary understanding of the role of β3GNT9, future research should collect the tumor tissue samples of glioblastoma patients in the local hospital to further verify the impact of β3GNT9 expression on patients’ survival time." (PMID 37771444, 2023). "The effects of β3GNT9 on the migration and invasion of glioblastoma were investigated through cell scratch and invasion assays." (PMID 37771444, 2023). "The relationship between β3GNT9 and the prognosis of glioblastoma was evaluated through univariate and multivariate COX regression analyses, and the survival analysis was conducted using the Kaplan-Meier method." (PMID 37771444, 2023). "On this basis, we propose that β3GNT9 can be used as a potential independent prognostic biomarker for patients with glioblastoma." (PMID 37771444, 2023). "The increased expression of β3GNT9 in glioblastoma can affect the immune microenvironment of glioblastoma and promote its migration and invasion." (PMID 37771444, 2023).
glioblastoma (continued). "We evaluated the expression of β3GNT9 in a variety of glioblastoma cell lines and normal astrocytes and found that β3GNT9 expression was higher in glioblastoma cell lines than in NHA cells (*P<0.05, **P<0.01)." (PMID 37771444, 2023). "Glioblastomas were divided into β3GNT9 high expression half and low expression half, and the differences between the 22 immune cell expression levels were analyzed using the CBIERSORT algorithm." (PMID 37771444, 2023). "Afterwards, we used clinical information and RNA sequencing data to explore the relationship between β3GNT9 expression and the prognosis of patients with glioblastoma." (PMID 37771444, 2023). "β3GNT9 can be used as a potential independent prognostic biomarker for patients with glioblastoma." (PMID 37771444, 2023). "Finally, high levels of β3GNT9 can serve as potential independent prognostic biomarkers for glioblastoma patients, promising a new direction of future immunotherapy for glioblastoma patients." (PMID 37771444, 2023). "The present study applied bioinformatics to analyze the molecular biological characteristics of human malignant glioma and found for the first time the high expression of β3GNT9 in glioblastoma, its correlation with prognosis, and its role in immune microenvironment." (PMID 37771444, 2023). "Moreover, the results of the differential expression analysis of TCGA database combined with GTEx database revealed significantly increased β3GNT9 expression in glioblastoma tissues." (PMID 37771444, 2023). "β3GNT9 expression in glioblastoma was analyzed using the GEPIA database." (PMID 37771444, 2023). "Regression analyses suggested that β3GNT9, involved primarily in glucosamine degradation and extracellular matrix receptor interaction, could be an independent prognostic factor for glioblastoma." (PMID 37771444, 2023). "In this sense, β3GNT9 can be regarded as a potential novel target for glioblastoma immunotherapy." (PMID 37771444, 2023). "GSEA was employed to predict the signaling pathway of β3GNT9 in glioblastoma." (PMID 37771444, 2023). "Furthermore, through univariate and multivariate COX regression analysis, we found the upregulation of β3GNT9 expression was an independent prognostic indicator of glioblastoma." (PMID 37771444, 2023). "CIBERSORT and GEPIA database analyses showed that β3GNT9 was correlated with tumor infiltrating immune cells such as T follicular helper cells, activating natural killer cells, monocytes, macrophages, and eosinophils, thus affecting the immune microenvironment of glioblastoma." (PMID 37771444, 2023). "Cell experiments confirmed that β3GNT9 was highly expressed in A172, U87MG and U251 cell lines (P<0.05), and promoted the migration and invasion of glioblastoma (P<0.05)." (PMID 37771444, 2023). "However, to date there is no report on the expression of β3GNT9 in glioblastoma and its relationship with clinical prognosis and immune-infiltrating cells." (PMID 37771444, 2023). "However, there is no report on the biological function and mechanism of β3GNT9 in the progression of glioblastoma." (PMID 37771444, 2023).
glioma (1 paper, 2023). A benign or malignant brain and spinal cord tumor that arises from glial cells (astrocytes, oligodendrocytes, ependymal cells). "We performed cell scratch and invasion assays to examine whether the downregulation of β3GNT9 affected the invasion or migration ability of glioma cells." (PMID 37771444, 2023).
prostate carcinoma (1 paper, 2023). A carcinoma that arises from epithelial cells of the prostate gland. "β3GNT9 was used as the candidate gene for androgen-independent prostate cancer." (PMID 37771444, 2023).
cancer (1 paper, 2014). A tumor composed of atypical neoplastic, often pleomorphic cells that invade other tissues. "We additionally identified recurrent mutations in RYR2, FMN1, B3GNT9 and PIEZO2 in our discovery set of cancers, but the importance of these genes for bladder carcinogenesis remains uncertain." (PMID 24777035, 2014).
tumor (1 paper, 2023). "The correlation between β3GNT9 and tumor immune infiltration was analyzed using the related modules of CIBERSORT and TIMER." (PMID 37771444, 2023). "Based on the immune infiltration analysis, we speculated that the high expression of β3GNT9 may lead to the change of activated NK cells and macrophages in tumor microenvironment, which in turn leads to poor prognosis of patients." (PMID 37771444, 2023). "The results revealed that β3GNT9 expression was significantly and positively associated with the infiltration levels of CD4+T cells, macrophages, dendritic cells (P<0.05), but negatively correlated with tumor purity, B cells, CD8+T cells, and neutrophils (P<0.05)." (PMID 37771444, 2023).
B3GNT9 also shares sentences with these, for which no sentence is quoted: bladder cancer (1 paper); chromophobe renal cell carcinoma (1); endometrial cancer (1); esophageal cancer (1); head and neck squamous cell carcinoma (1); Huntington disease (1); malignant glioma (1); ovarian serous cystadenocarcinoma (1); pancreatic cancer (1); Parkinson disease (1); thymic carcinoma (1).